CIP2A (cellular inhibitor of PP2A)
Description:
Acts as an inhibitor of protein phosphatase PP2A. Promotes anchorage-independent cell growth and tumor formation by preventing dephosphorylation of MYC, thereby stabilizing MYC in human malignancies. Together with TOPBP1, plays an essential role in the response to genome instability generated by the presence of acentric chromosome fragments derived from shattered chromosomes within micronuclei. Micronuclei, which are frequently found in cancer cells, consist of chromatin surrounded by their own nuclear membrane: following breakdown of the micronuclear envelope, a process associated with chromothripsis, the CIP2A-TOPBP1 complex tethers chromosome fragments during mitosis to ensure clustered segregation of the fragments to a single daughter cell nucleus, facilitating re-ligation with limited chromosome scattering and loss.
Synonyms: KIAA1524; NOCIVA; p90
Tractability: Antibody: its Gene Ontology location is reachable by antibodies, with high confidence; the Human Protein Atlas places it where antibodies can reach. PROTAC: ubiquitination databases record sites on it.
Gene: Protein-coding gene on chromosome 3 (108,549,864 to 108,589,644, reverse strand). Ensembl gene ENSG00000163507.
Subcellular location: Cytoplasm; Chromosome
Subcellular location (Human Protein Atlas): Cytosol; Basal body; Centrosome; Plasma membrane
Gene Ontology:
Molecular function: cadherin binding; protein binding; protein homodimerization activity; protein phosphatase inhibitor activity
Biological process: broken chromosome clustering; chromosome organization; DNA damage response
Cellular component: chromosome; cytoplasm; cytosol
Genetic constraint (gnomAD): Loss-of-function variants: 28 observed, 36.32 expected, observed/expected ratio (o/e) 0.77, 90% interval 0.57 to 1.06. The upper end of that interval is the gene's LOEUF score, 1.06, which puts it in group 4 of 6, group 1 being the genes least tolerant of losing a copy. Missense variants: 511 observed, 474.59 expected, observed/expected ratio (o/e) 1.08, 90% interval 1 to 1.16. Synonymous variants: 190 observed, 174.31 expected, observed/expected ratio (o/e) 1.09, 90% interval 0.97 to 1.23.
Homologues: Orthologues: chimpanzee CIP2A (99% identical), macaque CIP2A (98% identical), rabbit CIP2A (92% identical), pig CIP2A (92% identical), dog CIP2A (91% identical), rat Cip2a (88% identical), mouse Cip2a (87% identical), guinea pig CIP2A (84% identical), tropical clawed frog cip2a (66% identical), zebrafish cip2a (50% identical), Caenorhabditis elegans B0432.7 (23% identical). Paralogues in human: CCHCR1 (12% identical), CCDC57 (11% identical).
Diseases named in the same sentence as CIP2A in open-access papers:
CIP2A is named in the same sentence as 143 diseases in open-access papers, as found by Europe PMC text mining. Sharing a sentence is not in itself a finding about the gene and the disease. The quoted sentences say what the papers report.
breast carcinoma (55 papers, 2010 to 2025). "In breast cancer, the lncRNA-encoded micropeptide CIP2A-BP exhibited a direct binding affinity towards CIP2A, thereby the inhibition of PI3K-AKT-NFκB pathway led to a decrease in MMP2, MMP9, and Snail expression." (PMID 38542160, 2024). "Encoded by the ncRNA LINC00665, the 52-AA microprotein CIP2A-BP was identified as being downregulated by TGF-β in breast cancer cell lines, and low levels of CIP2A-BP expression are associated with poor survival in triple-negative breast cancer patients." (PMID 37213226, 2023). "Among its biological effects, CIP2A has been reported to regulate proliferation and apoptosis, invasion, cell cycle progression, and it has been associated with human breast cancer aggressiveness." (PMID 35329936, 2022). "In breast cancer, downregulated CIP2A-BP expression is associated with tumor metastasis and poor overall survival." (PMID 35233461, 2022). "Recent studies reported that CIP2A was closely linked to aggressive potential and sensitivity to doxorubicin treatments in breast cancer cells." (PMID 33948919, 2021). "Our findings indicate that EVE can cause disease progression via CIP2A, suggesting that CIP2A can be used as a potential biomarker to optimize treatment of HT‐resistant breast cancers." (PMID 32810922, 2020). "Using Kaplan–Meier survival plots, we report that high expression of CIP2A was associated with significantly reduced overall survival in patients with luminal A breast cancer." (PMID 32810922, 2020). "A different report has indicated that genistein, a phytoestrogen, downregulates CIP2A, and has associated its intake with reduced breast cancer risk." (PMID 29805747, 2018). "In the present study, we found that high expression of SET or CIP2A was associated with worse RFS in patients with ER-positive primary breast cancer receiving the adjuvant tamoxifen treatment." (PMID 30154367, 2018). "SET was overexpressed in about 50–60%, and CIP2A in about 90%, of breast cancers, and CIP2A overexpression was associated with triple negative, basal, and claudin-low tumor subtypes." (PMID 30341686, 2018). "It is important to note that mucinous mammary carcinomas with a good prognosis displayed low expression levels of CIP2A mRNA, similar to those for normal breast samples, indicating that CIP2A expression is linked to poor prognosis of human breast cancer." (PMID 30341686, 2018). "The data provide evidence for CIP2A as a risk factor for acquired lapatinib resistance, thus making it a potential target for novel breast cancer therapies." (PMID 28938602, 2017). "CIP2A is associated with human breast cancer aggressiveness and the overexpression of CIP2A has been shown to increase the proliferation of RAS/RAF mutated aggressive MDA-MB231 cell line." (PMID 25015035, 2014). "Of importance, it has been reported that serum CIP2A levels positively associate with poor prognosis and aggressive breast cancer phenotypes, and it could also be of interest to analyze serum p-AKT levels in forthcoming studies." (PMID 35329936, 2022). "High CIP2A expression was associated with reduced luminal A breast cancer patient survival." (PMID 32810922, 2020). "Interestingly, ETS1 and ELK1 have been shown to coordinately upregulate CIP2A, which encodes cancerous inhibitor of protein phosphatase 2A and leads to progression of gastric, cervical and breast cancer." (PMID 32079144, 2020). "Encoded by the KIAA1524 gene, CIP2A is overexpressed and may be prognostic in lung cancer, breast cancer, and ovarian cancer." (PMID 29261144, 2017). "Another study showed CIP2A associated with breast cancer aggressiveness." (PMID 25726524, 2015). "Furthermore, CIP2A has been reported to be associated with breast cancer aggressivity and to modulate sensitivity of breast cancer cells to bortezomib and doxorubicin treatments." (PMID 25726524, 2015).
breast carcinoma (continued). "Importantly, CIP2A overexpression is associated with clinical aggressiveness in human breast cancer and promotes the malignant growth of breast cancer cells." (PMID 25228280, 2014). "An increase in CIP2A expression was associated with doxorubicin resistance in breast cancer cells." (PMID 25015035, 2014). "CIP2A is a marker of reduced overall survival in certain subgroups of gastric cancer, and its expression associates with high grade and lymph node metastasis in breast cancer." (PMID 21897396, 2011). "Both ETS1 and CIP2A have been associated with clinical aggressivity in breast cancer." (PMID 21445343, 2011). "Lapatinib, a dual tyrosine kinase inhibitor used for ErbB2-positive breast cancer, inhibits CIP2A, resulting in the inactivation of Akt signaling and increased apoptosis in cancer cells." (PMID 41155727, 2025). "Functionally, we confirmed in vitro the role of CIP2A as a regulator of p-AKT levels in breast cancer cell lines, and the importance of the CIP2A/AKT axis was also validated in vivo." (PMID 35329936, 2022). "CIP2A have been described to regulate AKT activation in several tumor cell lines including breast cancer." (PMID 35329936, 2022). "Together with its reported ability to modulate AKT phosphorylation (p-AKT) status in several tumor types, the oncoprotein CIP2A has been described to induce breast cancer progression and drug resistance." (PMID 35329936, 2022). "In conclusion, our findings support novel therapeutic possibilities for a wide-spectrum of CIP2A/AKT-inhibiting drugs such asFTY720 in breast cancer to be used alone or in combination with standard anthracycline-based chemotherapy." (PMID 35329936, 2022). "In fact, functional inhibition of PP2A has been reported as a common alteration in breast cancer and CIP2A overexpression as a key event driving PP2A inactivation in this disease." (PMID 35329936, 2022). "In the last years, it has been progressively reported that CIP2A overexpression plays an oncogenic role and predicts adverse outcomes in a wide variety of human cancers including breast cancer." (PMID 35329936, 2022). "The existence of a CIP2A-AKT feedback loop in which AKT activation would be mediating a CIP2A upregulation in breast cancer cellshas been reported." (PMID 35329936, 2022). "In conclusion, our findings suggest that CIP2A overexpression is a key contributing event to AKT phosphorylation and highlights the CIP2A/AKT axis as a promising therapeutic target in breast cancer." (PMID 35329936, 2022). "At the clinical level, CIP2A overexpression hasbeen reported to predict poor outcome in breast cancer, with a special relevance in the TN subtype." (PMID 35329936, 2022). "In fact, our promising results showed by in vivo analyses using FTY720 would support that the CIP2A/AKT axis represents a novel therapeutic target in breast cancer." (PMID 35329936, 2022). "Altogether, these results confirm that CIP2A is involved in the p-AKT regulation ofour breast cancer cell lines." (PMID 35329936, 2022). "Our findings support the potential benefits of using CIP2A inhibitor as a therapeutic agent to treat doxorubicin-resistant breast cancer." (PMID 33948919, 2021). "Proliferation of breast cancer cell line MCF-7/ADR under effective doxorubicin concentrations after CIP2A silencing was examined by MTT assay." (PMID 33948919, 2021).
breast carcinoma (continued). "Although the expression of CIP2A is upregulated in hormone‐related cancers, such as breast cancer, little is known about the effects of specific molecular targeted therapy on the expression of CIP2A." (PMID 32810922, 2020). "CIP2A is a novel oncoprotein driving the malignant phenotype through and has been reported to be overexpressed in 39% of breast cancer cases." (PMID 32810922, 2020). "Although CIP2A is upregulated in hormone‐related cancers, such as breast cancer, little is known about potential anti‐tumor effects of downregulating CIP2A." (PMID 32810922, 2020). "For example, in lung and breast cancer, the overexpression of CIP2A resulted in resistance to the EGFR inhibitors lapatinib and erlotinib, while RNA interference-mediated CIP2A depletion sensitized the cells toward these compounds." (PMID 31214504, 2019). "CIP2A overexpression also resulted in resistance toward Chk1 kinase inhibitors in gastric adenocarcinoma and breast cancer cells." (PMID 31214504, 2019). "On the other hand, lapatinib downregulated CIP2A through regulation of protein stability in breast cancer cells." (PMID 31214504, 2019). "The overexpression of CIP2A mRNA was found in human breast cancers: 159 previously characterized human mammary tumors and 5 normal breast samples (P = 0.027)." (PMID 30341686, 2018). "Nevertheless, our protein analyses in the ErbB2-overexpressing breast cancer cells indicate a close correlation between CIP2A downregulation and RTK signaling inhibition." (PMID 28938602, 2017). "Data based on clinical samples reveal that CIP2A is overexpressed in various types of cancers, including breast cancer, and is indicative of poor prognostic outcomes." (PMID 28938602, 2017). "In this study, we investigated the effect of CIP2A on lapatinib-induced anti-cancer activities and resistance in ErbB2-overexpressing breast cancer cells." (PMID 28938602, 2017). "Cancerous inhibitor of protein phosphatase 2A (CIP2A) is a recently identified oncoprotein that is overexpressed in breast cancer." (PMID 28938602, 2017). "Lapatinib induces growth inhibition and apoptosis in ErbB2-overexpressing breast cancer cells by breaking the CIP2A-Akt feedback loop." (PMID 28938602, 2017). "As suggested by the critical role of CIP2A in lapatinib-induced inhibition of ErbB2-overexpressing breast cancer cells, we further demonstrated that CIP2A deregulation was associated with lapatinib resistance." (PMID 28938602, 2017). "Our study investigated the role of CIP2A in the anti-cancer efficacy of lapatinib in ErbB2-overexpressing breast cancer cells." (PMID 28938602, 2017). "Elk1 and CIP2A showed higher mRNA expression in tumor versus adjacent normal tissue from all breast cancer patient samples, from paired tumor/normal tissue and from the TNBC subpopulation." (PMID 26824320, 2016). "Depletion of CIP2A via siRNA in hepatocellular carcinoma, breast cancer and esophageal cancer not only decreased cancer cell proliferation but also sensitized cancer cells to chemotherapeutical agents like bortezomib and tumor necrosis factor." (PMID 26560124, 2015). "In concordance with the results showed by the PP2A activity assays, we found PP2A hyperphosphorylated together with SET and CIP2A markedly overexpressed in all the breast cancer cell lines analyzed." (PMID 25726524, 2015). "Of interest, CIP2A has been reported to modulate sensitivity of breast cancer cells to bortezomib and doxorubicin treatments." (PMID 25726524, 2015). "This is in accordance with previous report demonstrating decreased cell viability and anchorage independent growth following CIP2A inhibition in breast cancer cells." (PMID 25663244, 2015).
breast carcinoma (continued). "In this study, we show that PP2A is commonly inactivated in breast cancer and identify that CIP2A and SET overexpression together with PP2A hyperphosphorylation are key contributing mechanisms to inhibit PP2A in this disease." (PMID 25726524, 2015). "In contrast, we proved that extended inhibition of CIP2A expression, SET-induced PP2A inhibition and PP2A-phosphorylation by FTY720 treatment caused a deeply antitumoral effect in breast cancer cells." (PMID 25726524, 2015). "CIP2A in promoting AKT-mediated signaling through the effect on AKT-associated PP2A phosphatase activity has been confirmed in hepatocellular carcinoma, breast cancer and lung cancer cell lines." (PMID 26560124, 2015). "In this regard, more xenograft experiments using breast cancer cells with overexpression or downregulation of CIP2A and involving examination of apoptosis markers should be helpful." (PMID 25228280, 2014). "In breast cancer cells, a positive feedback loop between CIP2A and E2F1 had been shown to define the cell-intrinsic senescence sensitivity." (PMID 25015035, 2014). "A recent immunohistochemistry-based study demonstrated that CIP2A signature clustered with basal-type and HER2-positive breast cancer signatures and suggested that CIP2A is linked to these two subtypes of breast cancer." (PMID 25228280, 2014). "Out of 40 breast cancer cell lines, basal-like breast tumour cell lines exhibited the highest CIP2A overexpression." (PMID 24460909, 2014). "Using ribonucleic acid interference screens for autophagy-regulating phosphatases in human breast cancer cells, they have identified that CIP2A acts as a key modulator of mTORC1 and autophagy." (PMID 25015035, 2014). "Previously published literature has demonstrated that CIP2A silencing in cancer cells derived from different tissues, such as HNSCCs, renal cell carcinomas, and breast cancer can have effects on cancer cell invasion and anchorage-independent growth." (PMID 24019920, 2013). "In contrast, CIP2A has emerged as a novel oncoprotein and a growing number of reports have shown its overexpression in many human malignancies, including breast cancers." (PMID 22537901, 2012). "MRNA levels of CIP2A (as measured by a semi-quantitative nested PCR), decreased in a time-dependent manner upon treatment with bortezomib in the three sensitive breast cancer cell lines." (PMID 22537901, 2012). "Here we examined the molecular events associated with apoptosis and investigated the effects of bortezomib on p-Akt and CIP2A in bortezomib-treated breast cancer cells." (PMID 22537901, 2012). "To confirm that the effect of bortezomib on CIP2A has potentially relevant clinical implications in breast cancer, we assessed the in vivo effect of bortezomib on breast cancer xenograft tumors." (PMID 22537901, 2012). "Further studies as well as more samples are warranted to clarify the clinical role of CIP2A among various subtypes of breast cancer, in addition to TNBC subtypes." (PMID 22537901, 2012). "Very recently, an IHC-based study demonstrated that the CIP2A signature clustered with basal-type and HER2-positive breast cancer signatures and suggested that CIP2A is linked to these two subtypes of breast cancer." (PMID 22537901, 2012). "It would also be interesting to further investigate the prognostic role of CIP2A among various subtypes of breast cancer, in addition to TNBC subtypes, by large immunohistochemistry-based studies." (PMID 22537901, 2012). "Similar effects of bortezomib on p-Akt and CIP2A can be seen in a time-dependent manner in bortezomib-treated breast cancer cells." (PMID 22537901, 2012). "In contrast, bortezomib induced differential apoptotic effects in these breast cancer cells, which correlated with CIP2A downregulation." (PMID 22537901, 2012). "Except human breast cancer where CIP2A is overexpressed in 40% of patient samples, in all other studied cancer types the frequency is between 65 to 87% of patients." (PMID 21445343, 2011).